ICAM1 (intercellular adhesion molecule 1)
Diseases named in the same sentence as ICAM1 in open-access papers (continued):
Sharing a sentence is not in itself a finding about the gene and the disease.
tumor (continued). "Additionally, RT has known effects on the tumor vasculature, increasing endothelial expression of intracellular adhesion molecule-1 (ICAM-1) and vascular cell adhesion molecule (VCAM)." (PMID 34868010, 2021). "Therefore, we believed that ICAM-1 should be an essential checkpoint in the downstream of hsa_circ_0007456 in the regulation of the interaction between HCC tumor cells and NK cells." (PMID 33462208, 2021). "ICAM-1 is often expressed on a group of tumor cells, but some have its very limited expression." (PMID 34660784, 2021). "Agonist mAb stimulated tumor ECs, could increase expression of the ICAM-1, VCAM-1, and E-selectin on the surface of ECs, which are essential for CTLs to cross vessels and transport into TME." (PMID 34930293, 2021). "ICAM-1 expressed on neutrophils is important for neutrophil–tumor cell cluster formation." (PMID 34257370, 2021). "Furthermore, ICAM1 knockdown in MDA-MB-231 cells as well as TN3 PDXs dramatically inhibited the tumor cell aggregation." (PMID 34381029, 2021). "Finally, blocking ICAM1 with anti-ICAM1 neutralizing antibody significantly inhibited tumor cell cluster formation, TEM, and lung colonization." (PMID 34381029, 2021). "For example, LFA-1+CXCR4+CXCR5+ tumor cells may interact with ICAM-1+, CXCL12+/CXCL13+ endothelial cells, and ICAM-1+CXCL13+ microglia." (PMID 34944954, 2021). "Moreover, ICAM1 knockdown in both tumor cells and endothelial cells synergized to almost completely block the TEM." (PMID 34381029, 2021). "Similarly, the COX-2/PGE2 pathway, along with hypoxia, has been reported to contribute to OSCC metastases by increasing tumour cell migration and upregulation of intercellular adhesion molecule-1 (ICAM-1)." (PMID 34094895, 2021). "Since we previously demonstrated that CD44 mediates tumor cell aggregation, we next examined whether there is a regulatory correlation between CD44 and ICAM1 in tumor clustering." (PMID 34381029, 2021). "Since prior work has demonstrated that ICAM1 is expressed in endothelial cells and facilitates leukocyte endothelial transmigration, we examined if ICAM1 in tumor cells interacts with ICAM1 and other possible ligands in endothelial cells to promote trans-endothelial migration (TEM)." (PMID 34381029, 2021). "In 23 stage I–III CRC patients randomized to either low- (150 min/week) or high-dose (300-min/week) 6-month aerobic activity at 50–70% of the age-predicted maximum HR, circulating tumor cells was significantly reduced, along with BMI, insulin, and soluble ICAM-1." (PMID 33670492, 2021). "Furthermore, transendothelial migration of tumor cells was remarkably decreased by inhibition of ICAM-1; this was also reversed by administration of tamoxifen." (PMID 33754027, 2021). "Recently, the role of ICAM-1 in the interaction of tumor cells with LSECs has been described." (PMID 35008212, 2021). "Therefore, some scholars believe that the formation of the ICAM-1/LFA-1 complex is a positive feedback mechanism in the immune process of tumor cells, which helps to eliminate tumor cells in the body." (PMID 34386034, 2021). "In addition, immunofluorescence staining of MDA-MB-231 tumor cells showed higher expression of ICAM1 in the aggregated tumor cells compared to that of single tumor cells (24 h aggregation) (white arrows pointing to single tumor cells)." (PMID 34381029, 2021). "Machine learning-based algorithms and mutagenesis analyses identify ICAM1 regions responsible for homophilic ICAM1-ICAM1 interactions, thereby directing homotypic tumor cell clustering, as well as heterotypic tumor-endothelial adhesion for trans-endothelial migration." (PMID 34381029, 2021). "Instead, using artificial intelligence-based structural modeling in combination with experimental testing, our studies reveal that ICAM1 is capable of mediating homophilic interactions to drive homotypic CTC-CTC cluster formation as well as heterotypic tumor-endothelial cell adhesion." (PMID 34381029, 2021).
tumor (continued). "Thus it was concluded that halothane possessed tumor metastasis inhibiting property by down-regulating ICAM-1 expression in vitro." (PMID 33718164, 2021). "The MSI1/ICAM1 pathway plays a vital role in tumor resistance, including increased tumor invasion." (PMID 35154340, 2021). "Although PMN-tumor cell interaction is still an ongoing hypothesis, evidence shows that ICAM-1 expressed on tumor cells binds to Mac-1 (Integrin αΜ + Integrin β2) expressed on PMNs." (PMID 34168563, 2021). "They showed that treatment with either DNA methyltransferase (DNMT) or histone deacetylase (HDAC) inhibitors could increase ICAM-1 expression on tumour ECs and thus potentiate leucocyte infiltration in two different mouse tumour models." (PMID 33917287, 2021). "However, melanoma cells can be detected in single cell suspensions of tumor tissue, by combinations of ICAM-1, MUC18/MCAM (CD146) and the exclusion of CD45." (PMID 34910301, 2021). "Meanwhile, overexpression of ICAM-1 also significantly increased the number of adhered tumor cells and reversed the adhesion disadvantages of NSCLC cells conferred by CX3CL1-KD treatment in the presence of platelets, highlighting the dependent role of ICAM-1 in platelet-assisted NSCLC cell adhesion." (PMID 33754027, 2021). "While the molecular mechanisms underlying ICAM1’s function in tumor cells are not well defined, our study has successfully employed machine learning-based protein structure modeling to predict the ICAM1 dimerization residues for mutagenesis analyses." (PMID 34381029, 2021). "Therefore, leukocyte membrane proteins can target inflamed endothelium in the vicinity of the tumor tissue and also accumulate in their target cancer site by attachment to ICAM‐1 in the tumor microenvironment." (PMID 33898169, 2021). "On the other hand, the presence of ICAM-1 in some neoplastic cells located in the stroma, may indicate its participation in tumour cell spreading." (PMID 33372636, 2020). "Finally, anti-angiogenic drugs normalize tumor vasculature and induce the upregulation of the leukocyte adhesion molecules ICAM1 and VCAM1 on tumor endothelial cells, leading to increased T cell infiltration." (PMID 32752264, 2020). "Similarly, a co-culture study conducted with LSECs and C26 tumor cells showed that LSECs expressing ICAM-1 mediate tumor migration." (PMID 32848838, 2020). "ICAM-1 is also involved in tumour cell extravasation via remodelling of the actin cytoskeleton." (PMID 32982772, 2020). "Radiation-induced ICAM-1 mediates the transmigration of tumour-promoting CD11b + myeloid cells." (PMID 32135474, 2020). "It is regulated by endotoxin and some cytokines including TNF-α, IL-1β, and IFN-γ in vitro and in vivo; ICAM-1 plays an important role in promoting adhesion at the site of inflammation, controlling tumor progression and metastasis, and regulating immune responses in the body." (PMID 32089647, 2020). "Forced over-expression of the dual actin and LFA-1 binding protein TGLN2 in CTL yielded stronger killing activity in case of ICAM-1-expressing but not ICAM-deficient antigen-presenting tumor cells." (PMID 32092981, 2020). "Indeed, some studies report that the increased expression of ICAM-1 on tumour cells correlates with a more aggressive cancer." (PMID 32204481, 2020). "Induction of ICAM‐1 expression was confirmed via qPCR analysis on whole tumor RNA." (PMID 31912630, 2020). "LFA‐1 binds to ICAM‐1 (CD54) expressed by antigen‐presenting cells as well as by some tumor cells." (PMID 32620049, 2020). "LSEC expression of distinct adhesion molecules and growth factors could drive BM-EPCs recruitment, especially since BM-EPC homing to tumour tissue is thought to be via cellular adhesion molecules ICAM-1, VCAM-1, and VEGF." (PMID 32982772, 2020).
tumor (continued). "Western blot analysis of total cell lysates from the xenograft tumours (from a second cohort) showed that ICAM-1 protein expression was far lower in the xenografts when compared to in vitro cell cultures, and confirmed that there was little change in this expression level post-irradiation." (PMID 32135474, 2020). "ICAM-1 increased the sensitivity of tumor cells to CAR-T cells and thus killed tumor cells." (PMID 32626535, 2020). "Moreover, this precision medicine approach can be potentially utilized for the targeted treatment of PC and other ICAM1‐overexpressing cancers, and improve the other underway early phase clinical trials that use tumor‐targeting therapeutics." (PMID 33344137, 2020). "To investigate whether high ICAM1 expression is a clinically relevant finding in human PC, we conducted immunohistochemical (IHC) staining of ICAM1 in 80 human PC tumor tissues and 20 normal pancreas tissues." (PMID 33344137, 2020). "In the current study, we explored the potential mechanism of Porf-2 in tumor cell migration by screening several key proteins, such as adhesion molecules (ICAM1, VCAM1, E-cadherin), chemokines (CCL4, CXCL4) and their receptors (CXCR4/6/7), integrins (integrin α1/β1/β3), and MMPs (MMP-2/3/7/9)." (PMID 32676454, 2020). "The TME further supports effector T cell exclusion from the tumor by hindering the expression of adhesion molecules, such as ICAM-1 and VCAM-1, and inducing the expression of immunosuppressive molecules, such as FasL and PD-L1, at the surface of tumor-associated BECs." (PMID 33096748, 2020). "ICAM-1 is also involved in the process of tumor immune response." (PMID 33288735, 2020). "Tumor cells may gain resistance towards immune cell-mediated cytotoxicity when LFA-1/ICAM-1 is disrupted by matrix metalloproteinases 9 (MMP 9)." (PMID 32906721, 2020). "Moreover, low migration of T cells into the tumor due to overexpression of the endothelin B receptor (ET(B)R) on ECs was reverted by ET(B)R blocking, which restored immune cell infiltration by ICAM-1 activity." (PMID 33552076, 2020). "The identification of ICAM-1 as a potential biomarker of radiation treatment is of particular interest given the involvement of adhesion molecules in the immune response following tumour RT." (PMID 32135474, 2020). "VEGF, ICAM1, and VCAM1 were found to suppress tumor immunity by inhibiting the maturation of dendritic cells, and induce immunosuppressive cells such as regulatory T cells, tumor-associated macrophages, and myeloid-derived suppressor cells." (PMID 33364190, 2020). "ICAM1/GN-DU145 cells were able to form tumor tissue upon the neutralization of NK cells for 19 days after transplantation, and interestingly, ICAM1/GN-DU145-derived tumor growth was continuously promoted, like GN-DU145-derived tumor growth, after the discontinuation of NK cell neutralization." (PMID 31619256, 2019). "Given that angiogenic factors have been shown to cause decrease in ICAM-1 and VCAM-1 expression on tumor associated vessels, targeting angiogenesis could also increase T cell infiltration into tumors." (PMID 31231358, 2019). "ICAM-1 also mediates the migration of neutrophils into the tumor." (PMID 31261963, 2019). "The down-regulation of ICAM-1 after TGF-β1 stimulation underlines the tumor’s evasion from the immune system by reducing immune cell infiltration into the tumor microenvironment and tumor cell elimination by the tumor infiltrating lymphocytes (TILs)." (PMID 30863498, 2019). "ICAM-1 levels on tumor cells stimulate T-cell receptor-mediated cellular immune response." (PMID 31297450, 2019). "The fact that integrins αDß2, αMß2 and αXß2 also show interaction with ICAM-1 makes them possible alternative binding partners that tumor cells could make use of to accomplish adhesion." (PMID 30657059, 2019). "Thus, next, we studied the implication of endothelial ICAM-1 in the ability of tumor cells to transmigrate across monolayers of primary cultured LSECs." (PMID 31511625, 2019).
tumor (continued). "In the course of CAR T killing of tumor cells, low ICAM-1 tumors within or near high ICAM-1 tumors may become susceptible to CAR T cell killing due to induction of ICAM-1 by T cell cytokines such as IFN-γ." (PMID 31337787, 2019). "Indeed, macrophage infiltration has been demonstrated to correlate with ICAM-1 expressing tumor cells in oral squamous cell carcinoma." (PMID 31231358, 2019). "Our findings serve as a basis for forming new tumorigenic mechanism hypotheses and suggest that NANOG-mediated ICAM1 downregulation is a key factor allowing the formation of tumor tissue via the evasion of NK cell attack." (PMID 31619256, 2019). "Thus, we next utilized our in vivo model of liver metastasis to analyze how in vitro alteration of tumor cell response to ICAM-1 modifies tumor ability to develop liver metastasis." (PMID 31511625, 2019). "CD11b/CD18 and, to a minor extent, ICAM-1 significantly polarized to the IL-33 EO-tumor cell synapses, whereas they were expressed evenly on the cell membrane of IL-5 EO conjugated with target tumor cells." (PMID 31717819, 2019). "Blockage of endothelial ICAM-1 reduced tumor transmigration by 50%." (PMID 31511625, 2019). "Interestingly, IL-35 treatment of human pancreatic ductal adenocarcinoma (PDAC) cell lines induced ICAM1 expression indicating a role for IL-35 in tumor metastasis." (PMID 31681561, 2019). "Likewise, we identified that ICAM-1 expression is attenuated in metastatic cells compared to primary tumor cells." (PMID 31297450, 2019). "Given that MUC-1 which is often expressed on tumor cells can also interact with ICAM-1, circulating cancer cells can adhere to endothelial cells which may represent the first step in metastases formation." (PMID 31231358, 2019). "There is still controversy regarding the contribution of ICAM-1 expression to tumor progression." (PMID 31297450, 2019). "In addition to priming, LFA-1 and integrin αE(CD103)β7 expressed on CD8+ T cells play important roles for CD8+ T cell cytotoxicity towards tumor cells expressing ICAM-1 and E-cadherin." (PMID 31231358, 2019). "Hence, differential CCR7 expression after ICAM-1 blockade is transient and occurs in tumor stroma infiltrating lymphocytes." (PMID 30258446, 2018). "Finally, cell adhesion molecules, such as ICAM1, were produced by tumor cells in a NF-κB-dependent manner." (PMID 29772694, 2018). "Moreover, induced overexpression of ICAM1 in tumor cells have been shown to result in reduced tumor growth correlated with increased lysis by tumor infiltrating lymphocytes." (PMID 30082828, 2018). "Therefore, exposure to anti-ICAM-1 impedes the formation of leukocyte clusters inside the tumor tissue." (PMID 30258446, 2018). "This indicated that in the iLID3W mice, in contrast to controls, tumor associated neutrophils (TAN) did not lose the expression of markers characteristic of the pro-inflammatory (N1) phenotype (high ICAM-1 and low CCL5 and VEGF expression)." (PMID 29644002, 2018). "Similarly, TNF-α-stimulated upregulation of ICAM-1 in peritoneal mesothelial cells has been described in an animal tumour mode." (PMID 29772648, 2018). "Notably, radiation has been shown to increase the expression of E-selectin and ICAM-1 in human endothelial cells, thus modifying the tumor vasculature to allow more robust immune-cell infiltration." (PMID 30558196, 2018). "Sorted CD8+ T cells from PB of healthy donors were cultured in vitro on a plate coated with ICAM-1 Fc chimera to mimic the engagement of ICAM-1-mediated engagement of tumor cells binding to LFA-1 on the surface of CD8+ T cells, in the presence of soluble human recombinant TGFβ2 and anti-CD3." (PMID 29966014, 2018). "Furthermore, we observed the same effect when ICAM-1 was blocked 48 h after intravenous injection of naïve T-cells recognizing tumor antigens." (PMID 30258446, 2018).
tumor (continued). "Since immunotherapy activates the immune system, and ICAM-1 blockade diminishes tumor retention and improves lymphocyte recirculation, patients with metastasis, multiple or recurrent lesions could benefit from this combination." (PMID 30258446, 2018). "In this sense, T-cell integrins and their cognate ligands expressed on target cells, mainly lymphocyte-function-associated antigen-1 (LFA-1)/intercellular adhesion molecule-1 (ICAM-1) and CD103/E-cadherin play a relevant role in the interactions between cytotoxic T lymphocytes and tumor cells." (PMID 30258446, 2018). "We demonstrated that ICAM1 expression was inducible in tumor cells upon pro-inflammatory stimuli which might be important for the extravasation process from the blood vessels." (PMID 30082828, 2018). "We speculate that ICAM1 expression can be upregulated by cytokines in the tumor microenvironment prior to intravasation into the circulation." (PMID 30082828, 2018). "Interestingly, we detected ICAM1 positive tumor cells exclusively in triple negative and HER2 enriched subtypes." (PMID 30082828, 2018). "These hypoxic neo-angiogenic vessels in the tumor are dysfunctional in the expression of homing molecules such as adhesion molecules (e.g., ICAM-1, VCAM-1, E- and P- selectins) and chemokines, and consequently less capable of supporting T cell flux and extravasation." (PMID 30126117, 2018). "Furthermore, immunohistochemical analyses revealed ICAM1 immunoreaction in tumor cells of more aggressive subtypes, including HER-2 enriched and triple negative tumors." (PMID 30082828, 2018). "To assess the capacity of CCL21 + ICAM1-stimulated CD8+ T-cells to suppress tumor development in vivo, we treated mice bearing B16-ovalbumin tumors with T-cells that were pre-cultured for 7 days on either uncoated substrates, or on substrate-immobilized CCL21 + ICAM1." (PMID 29942308, 2018). "In addition, we analyzed ICAM1 expression in tumor metastasis (n = 6) within dissected lymph nodes (LN) of these 23 patients." (PMID 30082828, 2018). "Interestingly, all tumors with ICAM1 positive tumor cells (n = 4) had high amount of immune cell infiltration and all were TLS positive." (PMID 30082828, 2018). "This Mac-1/ICAM-1 interaction inhibits DC maturation and may blunt the ability of DCs in an inflamed tumor microenvironment to prime antitumor T cells." (PMID 29527513, 2018). "Questioning the proposed TNBC-specific expression profile of ICAM1, we investigated whether a proinflammatory stimuli could mimic the milieu found in the tumor microenvironment and result in overexpression of ICAM1 also in hormone sensitive subtypes." (PMID 30082828, 2018). "Among the TNBC tumors tested, 63% of the samples showed positive ICAM1 staining in tumor cells." (PMID 30082828, 2018). "Consequently, T-cells cultured on CCL21 + ICAM1-coated substrates exhibited an improved killing of cultured cancer cells, and markedly elevated tumor suppressive activity, in vivo." (PMID 29942308, 2018). "No positive correlation could be found between lymph node status, tumor grade, and ICAM1 positive tumors." (PMID 30082828, 2018). "In addition, RT can induce the expression of Fas and ICAM-1 on tumor cells, rendering them more sensitive to T cell-mediated lysis, which can be blocked by the administration of anti-FasL." (PMID 30115069, 2018). "In general, the high levels of expression of ICAM-1 by cancer cells could promote an increased level of transcellular migration of leukocytes to the tumor site." (PMID 30348199, 2018). "We propose that ICAM-1-mediated homotypic T-lymphocyte aggregation may serve as a tumor-mediated immune retention mechanism entrapping activated CD8+ T cells in the tumor microenvironment." (PMID 30258446, 2018). "With these results we demonstrate how transient blockade of ICAM-1 may improve intratumoral T cell migration to the lymph nodes and favor the intra tumor expression of one of the most important lymph node chemotactic receptors." (PMID 30258446, 2018).